INS (insulin)
Diseases named in the same sentence as INS in open-access papers (continued):
Sharing a sentence is not in itself a finding about the gene and the disease.
Insulin resistance (continued). "Insulin resistance is defined as a reduction in tissue insulin responsiveness due to reduced insulin receptor expression and blockage of insulin signaling pathways in a variety of cells (mostly in the liver, muscles, and adipose tissues)." (PMID 34299201, 2021). "Of interest, better DNL responders had statistically greater degrees of glucose intolerance and insulin resistance at baseline along with trends toward higher plasma fasting glucose, insulin, and TG levels." (PMID 35028615, 2021). "Adipose tissue insulin resistance is characterized by defective insulin‐mediated glucose transport, a decreased capacity for lipid uptake, and a failure to suppress lipolysis and inflammation, resulting in elevated plasma free fatty acids (FFA) and cytokines." (PMID 33463892, 2021). "Insulin circulates at concentrations proportionate to total body fat, as a result of increasing peripheral insulin resistance with increased fat mass." (PMID 33777773, 2021). "Ablation of these CD11c+ proinflammatory macrophages decreases AT inflammation and interferes with the development of insulin resistance, suggesting that macrophages are key mediators of insulin sensitivity." (PMID 34248937, 2021). "The constant of the hyperbolic curve, which is the product of insulin secretion and insulin sensitivity, is frequently called the disposition index (DI), reflecting β-cell response compensated for insulin resistance." (PMID 34917033, 2021). "Since baseline glucose tolerance, insulin sensitivity, and blood pressure were significantly impaired compared to the lean mice, we concluded that the obesity-induced pathological insulin resistance-related conditions were sufficiently established." (PMID 34959926, 2021). "Insulin resistance is a major feature of type 2 diabetes and refers to insulin dysfunction in peripheral tissues, such as skeletal muscles, liver, and adipose tissues." (PMID 33799458, 2021). "Although it has been well described that type 2 diabetes is a disease of insulin resistance, a large amount of the medical therapies that physicians use are based around the premise of giving the patient more insulin." (PMID 33531076, 2021). "Insulin resistance, a medical status in which the insulin production is sufficient but the body is failing to make use of insulin properly, is a hallmark of Alzheimer’s disease (AD), type II diabetes (T2D), and Parkinson’s disease (PD)." (PMID 35111696, 2021). "This stems from evidence in patients with type 2 diabetes, where immune cell infiltration of visceral adipose tissue results in the pathological disruption of insulin signalling, contributing to insulin resistance." (PMID 33923959, 2021). "Increased serum levels of irisin, betatrophin and insulin were also seen in diabetic rats submitted to high-intensity interval training, which attenuated insulin resistance." (PMID 33672171, 2021). "Our results indicate that supplementation with ProbiogluTM significantly improved glucose tolerance, glycemic levels, insulin levels, and insulin resistance (HOMA-IR)." (PMID 34166387, 2021). "Pairwise Spearman correlation analysis showed that HCA species inversely correlated with BMI, fasting and post-load glucose, insulin levels and insulin resistance shown by HOMA-IR." (PMID 33674561, 2021). "Conversely, direct injection of an adenovirus expressing active Drp1 in the DVC caused insulin resistance in rats fed a regular chow (RC) diet and prevented DVC insulin from lowering HGP." (PMID 33227495, 2021). "The liver-specific IR knockout mice display severe insulin resistance and defects in insulin clearance." (PMID 33772019, 2021). "In turn, the resultant excessive circulating free fatty acids exacerbate insulin resistance by disrupting insulin signaling and glycogen synthase." (PMID 34055942, 2021). "Fasting glucose, insulin, and homeostasis model assessment of insulin resistance (HOMA-IR) levels were also increased in AAV-Mir20b administrated HFD-fed mice." (PMID 34964438, 2021).
Insulin resistance (continued). "Blueberry supplementation also improved the insulin sensitivity and diminished insulin resistance in HFD fed rats." (PMID 34208379, 2021). "Liver, the main site where insulin resistance occurs, is a vital organ that regulates metabolism and insulin sensitivity, and plays a key role in controlling insulin sensitivity." (PMID 34262422, 2021). "Increased ROS leads to increased oxidative stress, impairs both B cell function and insulin signaling, thereby accelerating insulin resistance." (PMID 34746831, 2021). "For example, healthy insulin levels and insulin sensitivity plus exogenous OCn = X, whilst hyperinsulinaemia and insulin resistance plus exogenous OCn = Y." (PMID 34572351, 2021). "RSG (Avandia®, GlaxoSmithKline) is a potent TZD insulin sensitizer that decreases hyperglycemia by reducing insulin resistance in patients with T2D4." (PMID 33990655, 2021). "The PI3K pathway regulates insulin signal transduction and glucose homeostasis, while over-activity of the JNK pathway is linked to insulin resistance and type-2-diabetes." (PMID 34201794, 2021). "Compared to the control group, the insulin resistance index in the lychee seed extract group was dramatically reduced, which in turn increased the insulin sensitivity index progressively." (PMID 34690773, 2021). "Insulin and insulin resistance determined by homeostatic model assessment (HOMA-IR-index) were higher in obese controls than in PWS subjects and lean controls." (PMID 34768690, 2021). "Insulin resistance is the condition in which a cell, tissue, or body of an organism cannot adequately respond to normal levels of insulin." (PMID 34445300, 2021). "The mechanisms that can sustain hyperglycemia induced by everolimus include the reduction of production and secretion of insulin, the increase of peripheral insulin resistance, and a possible increase of hepatic gluconeogenesis." (PMID 34199977, 2021). "For example, IGF-1 mimics some of the insulin actions and promotes insulin sensitivity, while GH is anti-insulinemic and promotes insulin resistance; IGF-1 promotes fat deposition, while GH is lipolytic." (PMID 34899820, 2021). "Protein tyrosine phosphatase 1B (PTP1B) is a non-trans membranous protein that acts as a major negative regulator of insulin signaling pathways, thereby mediating insulin resistance." (PMID 34093192, 2021). "Individuals in the MOD cluster were characterized by younger age at diagnosis (mean 54.8 years old) and obesity (mean BMI 26.9 kg/m2), but with moderate insulin release and insulin resistance status (median HOMA-β 57.0, HOMA-IR 2.7)." (PMID 35154005, 2021). "Existing evidence has proved that sphingomyelin contributed to the development of insulin resistance by modifying the insulin signaling pathway." (PMID 33674681, 2021). "Since HFD consumption has been widely associated with the occurrence of brain insulin resistance, we firstly tested the ability of pretreated IPA protocol to alter the insulin cascade in cells." (PMID 33916835, 2021). "Accordingly, liver-specific and global Cc1−/− null mice developed chronic hyperinsulinemia and insulin resistance emanating from impaired insulin clearance." (PMID 34440862, 2021). "In skeletal muscle, insulin resistance is characterised by reduced intracellular insulin-stimulated glucose uptake and handling due to reduced insulin-induced GLUT4 translocation to the cell membrane and subsequent glycogen synthesis." (PMID 33387681, 2021). "In high-fat fed dogs who developed insulin resistance, reduced insulin clearance was more important in maintaining long-term hyperinsulinemia than increased insulin secretion." (PMID 34206745, 2021). "One of the main reasons for weight gain attributed to night-shift work is that excessive secretion of cortisol and interleukins, together with increased insulin concentrations, can lead to abdominal fat buildup, lipid disorders, and insulin resistance." (PMID 34842622, 2021).
Insulin resistance (continued). "NES was associated with higher fasting plasma insulin concentration and the HOMA-IR (Homeostatic Model Assessment for Insulin Resistance) index (calculated using the following formula: FPG (mmol/L) times fasting serum insulin (mU/L) divided by 22.5)." (PMID 34684381, 2021). "In conclusion, mitochondrial dysfunction will cause ectopic lipid accumulation, thereby resulting in the significant increase of ceramide and diacylglycerol, which will directly or indirectly suppress insulin signaling pathway to induce insulin resistance." (PMID 34414181, 2021). "Insulin signaling is negatively regulated by PTP1B and increased activity and expression are implicated in the insulin resistance pathogenesis." (PMID 33672051, 2021). "While upregulation of PPARγ expression is linked to obesity, activation of this receptor has also been shown to enhance insulin sensitivity and accelerate blood triglyceride clearance, hence preventing insulin resistance and hypertriglyceridemia." (PMID 34072832, 2021). "Patients with higher insulin sensitivity were more susceptible to benefit from a decrease in TAR and an increase in TIR than patients with insulin resistance." (PMID 33136439, 2021). "Insulin acts upon immune cells and therefore, systemic insulin resistance can have a substantial impact on the functioning of the adaptive and innate immune system." (PMID 33920604, 2021). "Individuals with peripheral insulin resistance also show blunted cerebral responses to insulin, suggesting central insulin resistance." (PMID 34331964, 2021). "Exogenous insulin has long been a diabetes treatment, in cases of high insulin resistance, this would become increasingly less effective." (PMID 34489979, 2021). "The pathogenesis of β-cell dysfunction leading to insulin resistance and impaired insulin secretion seen in type 2 diabetes is incompletely understood." (PMID 34748564, 2021). "Studies in mice showed that lower concentrations of OC caused decreased proliferation of pancreatic beta cells, resulting in reduced insulin secretion and development of insulin resistance." (PMID 34769010, 2021). "The insulin secretion by the activation of pancreatic β-cells intensifies the muscle and adipose peripheral insulin resistance." (PMID 33804729, 2021). "Insulin resistance is an impaired biological response to insulin stimulation in target tissues, primarily liver, muscle, and adipose tissue." (PMID 34803916, 2021). "Overall, these data identified DUSP9 as a key regulator of insulin signaling and highlighted its potential role in insulin resistance and metabolic diseases by dephosphorylating kinases involved in metabolic processes, glucose uptake and storage." (PMID 34768967, 2021). "In recent years, SIRT1 has been found to positively regulate insulin secretion by islet β-cells, inhibit inflammation and improve insulin resistance." (PMID 34630099, 2021). "IL-6 also represents a link to insulin resistance, as it has been shown to suppress metabolic processes stimulated by insulin in hepatocytes, possibly induced by SOCS3 expression." (PMID 33810619, 2021). "The accumulation of insulin in neurons is directly related to the level of Tau hyperphosphorylation and follows the progression of tauopathy; in addition, the accumulation of insulin is related to insulin resistance and reduction in IR level." (PMID 34576151, 2021). "A diverse range of reduced responses to insulin in the brain and peripheral tissues is designated as insulin resistance." (PMID 34356604, 2021). "We observed that fetuin-A was positively correlated with fasting glucose and insulin levels, insulin resistance and increased WC." (PMID 34645898, 2021). "Insulin resistance (IRES) occurs when the excess of glucose in the blood induces an increase in insulin release that makes the target organs resistant to its action." (PMID 33467677, 2021).
Insulin resistance (continued). "Ang II is involved in the pathogenesis of insulin resistance through the induction of key signaling elements of the insulin AKT (also known as protein kinase B) pathway." (PMID 34483960, 2021). "The pathogenesis of type 2 diabetes (T2DM) mellitus is complex, but it is acknowledged that the combination of defective insulin secretion and insulin resistance plays a critical role in the development of T2DM." (PMID 34867781, 2021). "This can lead to reduced insulin-mediated glucose uptake in muscle cells in vitro and in animal models, resulting in reduced insulin sensitivity and higher insulin resistance in the offspring." (PMID 34296321, 2021). "Apparently, with a compromised insulin signaling cascade during insulin resistance, glycolysis also becomes compromised." (PMID 33953863, 2021). "Recently, several clinical studies have confirmed that curcumin can significantly improve insulin resistance in diabetic patients and has insulin-sensitizing effects." (PMID 34955862, 2021). "This index was more reliable to assess insulin resistance than the fasting glucose/insulin ratio and was an independent predictor of cardiovascular disease." (PMID 34836231, 2021). "Stress is associated with hypothalamic-pituitary-adrenal dysregulation, increased blood levels of insulin, insulin resistance, and visceral fat accumulation." (PMID 34063694, 2021). "Type 2 diabetes (T2D) is a metabolic disease characterised by a failure in the signalling cascade of the insulin hormone, preventing the partial or total capture of glucose inside body cells, which leads to what is called insulin resistance." (PMID 34886369, 2021). "Further, the use of individual clinical parameters in isolation, such as body mass index (BMI) or insulin dose requirements are crude indicators of insulin resistance in T1D." (PMID 33730349, 2021). "Intensive care interventions, such as the use of inotropes and corticosteroids, also increase insulin resistance and suppress insulin secretion." (PMID 34368024, 2021). "The dietary management of insulin resistance with lettuce and treatment using avicularin all enhance insulin sensitivity at varying degrees via different modes of action." (PMID 33953863, 2021). "All pediatric subjects in this study presented normoglycemia, while the state of insulin resistance driven by the high circulating insulin concentrations observed in the UHO group likely reflects an attempt to maintain their euglycemia." (PMID 34457110, 2021). "Glucocorticoids cause hepatic insulin resistance, resulting in increased hepatic glucose output and induce peripheral insulin resistance, which predominantly reflects insulin action in skeletal muscle." (PMID 33859617, 2021). "At present, the treatment for insulin resistance in PCOS patients is mainly to increase insulin sensitivity in peripheral tissues, and the representative drug is metformin." (PMID 34457027, 2021). "At the end of the experiment, high-fasting blood glucose, high-fasting insulin, the onset of insulin resistance and blood glucose recovered slowly after an OGTT, and high AUCglucose values were found in the HFD group." (PMID 34574191, 2021). "Given the comparable development of insulin resistance and impaired action of insulin and ghrelin in the ARC of IR∆Tan and obese, HFD-fed mice, we next aimed at comparing molecular changes occurring in tanycytes of both mouse models." (PMID 34931084, 2021). "Concerning glucose and plasma lipid levels, although fasting glucose was not different among the three groups, women with PCOS had higher fasting insulin, glycosylated hemoglobin, and homeostasis model assessment of insulin resistance (HOMA-IR)." (PMID 33773586, 2021). "Insulin resistance is a consequence of the impairment of insulin signaling in insulin-responsive cells, like hepatocytes, myocytes and adipocytes." (PMID 33920604, 2021).
Insulin resistance (continued). "Obesity and insulin resistance result in abnormally high rates of lipolysis in the fed state, driven by the impaired action of insulin to inhibit lipolysis, as well as by the chronic inflammation characteristic of obese states." (PMID 35211087, 2021). "Compared with NGT women, GDM women with high insulin resistance had a greater risk of having LGA and cesarean delivery while GDM women with lower insulin secretion or both abnormalities had comparable pregnancy outcome with those in NGT women." (PMID 34893662, 2021). "The extracts administration led to a significant decrease in the level of glucose, insulin and triacylglycerols in blood serum of adult mature inbred rats with insulin resistance induced by the fructose-enriched diet." (PMID 34445028, 2021). "In the case of insulin resistance, serine/threonine competitively inhibits tyrosine phosphorylation, of which serine/threonine 307 has an important negative regulatory effect on the insulin pathway." (PMID 33824679, 2021). "T2D is a complex pathophysiological disease that involves many metabolic pathways, but its main characteristic is the failure of β-cell insulin secretion, frequently in a background of insulin resistance." (PMID 33505497, 2021). "The major feature of T2DM is insulin resistance, a defective response to physiological or increased endogenous or exogenous insulin concentration, that leads to hyperglycemia and hyperinsulinism." (PMID 34208589, 2021). "Induction of miR-96 by dietary saturated fatty acids impairs insulin signaling and exacerbates hepatic insulin resistance through the suppression of INSR and IRS-1." (PMID 34199293, 2021). "Insulin resistance was defined as “a state in which a greater than normal amount of insulin is required to elicit a quantitatively normal response”." (PMID 33681089, 2021). "The induction of insulin resistance by statins determines an abnormally reduced response of insulin-sensitive cells to normal levels of circulating insulin, as noticed in hepatocytes, adipocytes, and myocytes." (PMID 34575946, 2021). "Some studies have shown that a short-term period on a high protein diet can improve insulin sensitivity in subjects with obesity and insulin resistance." (PMID 33923531, 2021). "The relationship of ADH1B expression, in adipose tissue and subcutaneous adipocytes, with BMI and insulin activity underscores the importance of its potential role in obesity and insulin resistance." (PMID 33479282, 2021). "For instance, the dietary content of advanced glycation end products (AGE) has been investigated and a recent meta-analysis has reported that a poor diet of AGE has beneficial effects on fasting insulin and insulin resistance." (PMID 35056936, 2021). "Excessive production of ROS can exacerbate and contribute to the pathogenesis of insulin-resistance and impaired insulin secretion." (PMID 34829598, 2021). "Numerous clinical studies have demonstrated that metformin decreases insulin resistance and improves intracellular signaling of insulin, reduces glucotoxicity and lipotoxicity." (PMID 33562458, 2021). "Though, several factors contribute to the onset and aggravation of insulin resistance, numerous studies have implicated the loss of function of insulin receptor substrates (IRS) as the mechanistic link to the dysregulation of insulin signaling." (PMID 33953863, 2021). "In the current study, a significantly high value of HOMA-IR in the HFD control group due to the elevation of blood glucose level and insulin concentration indicated a development of insulin resistance." (PMID 34975503, 2021). "Possible pathophysiologic mechanisms behind this phenomenon include impaired insulin signalling or insulin resistance in the brain." (PMID 34540446, 2021). "Chronic insulin stimulation degrades insulin receptor substrate 1 and 2 (IRS1 and IRS2) protein and causes insulin resistance in vitro." (PMID 33547878, 2021).